FLYWCH2 (FLYWCH family member 2)
Tractability: PROTAC: ubiquitination databases record sites on it; its protein half-life has been measured.
Gene: Protein-coding gene on chromosome 16 (2,883,165 to 2,903,099, forward strand). Ensembl gene ENSG00000162076.
Subcellular location (Human Protein Atlas): Nucleoplasm
Gene Ontology:
Molecular function: RNA binding
Genetic constraint (gnomAD): Loss-of-function variants: 2 observed, 5.82 expected, observed/expected ratio (o/e) 0.34, 90% interval 0.14 to 1.08. That is too few expected variants to judge how well the gene tolerates losing a copy. Missense variants: 192 observed, 189.5 expected, observed/expected ratio (o/e) 1.01, 90% interval 0.9 to 1.14. Synonymous variants: 87 observed, 82.29 expected, observed/expected ratio (o/e) 1.06, 90% interval 0.89 to 1.26.
Homologues: Orthologues: chimpanzee FLYWCH2 (98% identical), dog FLYWCH2 (75% identical), macaque FLYWCH2 (74% identical), pig FLYWCH2 (73% identical), mouse Flywch2 (71% identical), rat Flywch2 (70% identical). Paralogues in human: FLYWCH1 (55% identical).
Diseases named in the same sentence as FLYWCH2 in open-access papers:
FLYWCH2 is named in the same sentence as 1 disease in open-access papers, as found by Europe PMC text mining. Sharing a sentence is not in itself a finding about the gene and the disease.
FLYWCH2 shares sentences with these, for which no sentence is quoted: breast carcinoma (1 paper).